RET (ret proto-oncogene)
Diseases named in the same sentence as RET in open-access papers (continued):
Sharing a sentence is not in itself a finding about the gene and the disease.
thyroid cancer (continued). "RET fusions are mutually exclusive with BRAF and RAS gene mutations in thyroid cancer, consistent with its role as a driver oncogene." (PMID 35510953, 2022). "Combined inhibition of FGFR and RET prevented the development of adaptive resistance to RET inhibitors, reduced cell viability, and decreased tumor growth in cellular and animal models of CCDC6-RET–rearranged thyroid cancer." (PMID 35510953, 2022). "But the fusion of CCDC6 and RET in thyroid cancer cells abrogates the ability to combine with CREB1 so as to activate CREB1." (PMID 36186907, 2022). "It has recently been shown to play an important role in thyroid cancer, with related genes, such as RET/PTC, RAS, and BRAF, acting through NF-κB." (PMID 36675746, 2022). "Clinical studies have determined that Lenvatinib blocks VEGF- and FGF-driven angiogenesis, KIT-dependent angiogenesis, RET-fusion/RET freak tumorigenesis, and VEGFR3-associated lymphangiogenesis in preclinical human thyroid cancer models." (PMID 35457226, 2022). "Using zebrafish we built a patient-specific avatar of RET-rearranged thyroid cancer and demonstrated conservation of gene expression, sensitivity to RET inhibition, and synergy between RET and FGFR inhibitors in vivo." (PMID 35510953, 2022). "After a median time of 1 year, 82% of MTC patients previously treated with vandetanib and/or cabozantinib, 92% of the naïve and 64% of other RET-mutant thyroid cancers remained free of progression." (PMID 35422765, 2022). "Researchers conducted multiple clinical trials of Vandetanib, Cabozantinib, and Lenvatinib in RET fusion-positive thyroid cancer." (PMID 36582799, 2022). "Two phase I/II studies were built to evaluate the efficacy and safety of selpercatinib and pralsetinib in treating patients with RET-mutant thyroid cancers." (PMID 35422765, 2022). "Since discovery of the first RET fusion in thyroid cancers, at least 13 fusion partners have been identified in papillary thyroid cancers, the most common of which are coiled-coil domain containing 6 (CCDC6-RET) and nuclear receptor co-activator 4 (NCOA4)-RET." (PMID 35957881, 2022). "The study also analyzed patients with RET-mutated and RET fusion-positive MTC patients, where ORR for previously treated, treatment-naïve and fusion-positive previously treated thyroid cancer patients were 60%, 71%, and 89%, respectively." (PMID 36358717, 2022). "Further studies will be required to understand the sensitivity of alternative RET fusion proteins in thyroid cancer and to examine RET fusions in other cancer contexts, including lung adenocarcinoma." (PMID 35510953, 2022). "In the thyroid cancer samples BRAF mutations co-occurred less frequently than expected with mutations in NRAS, HRAS, RET, PTEN, NF1 and KRAS." (PMID 36275468, 2022). "The receptor tyrosine kinase (RET) inhibitors, selpercatinib and pralsetinib, were approved by the FDA for advanced or metastatic RETmutation-positive medullary thyroid cancer (MTC) or RET gene fusion-positive thyroid cancer." (PMID 34981751, 2022). "Analysis of metastatic tumor tissue isolated from lung and bone specimens confirmed the presence thyroid cancer and a RET gene rearrangement." (PMID 35510953, 2022). "Our aim was to identify patients with NTRK fusion-positive thyroid cancer and RET fusion/mutation-positive thyroid cancer who can benefit from treatment with NTRK and RET inhibitors." (PMID 34981751, 2022). "We constructed a transgenic model of RET-rearranged thyroid cancer using genetic approaches in zebrafish." (PMID 35510953, 2022). "In order to understand resistance mechanisms arising after treatment with RET inhibitors, we performed a comprehensive molecular and genomic analysis of a patient with RET-rearranged thyroid cancer." (PMID 35510953, 2022).
thyroid cancer (continued). "Several mutations, including RAS or RET, as well as BRAF signaling, are associated with thyroid cancer." (PMID 35630083, 2022). "Genetic alterations in RET lead to activation of ERK and AKT signaling and are associated with hereditary and sporadic thyroid cancer and lung cancer." (PMID 35510953, 2022). "Selective RET inhibitors have been approved for advanced RET-altered thyroid cancer and non-small cell lung cancer." (PMID 35600349, 2022). "In 19 patients with previously treated RET fusion-positive thyroid cancer, selpercatinib showed a 79% objective response and 64% of 1-year PFS rate, with a low discontinuous rate (2%, 12 out of 531) due to adverse events." (PMID 36091770, 2022). "The remaining patients (19/162 – 11.7%) showed a RET fusion–positive thyroid cancer (PTC, poorly differentiated thyroid carcinoma, Hürthle cell carcinoma and ATC)." (PMID 35422765, 2022). "The most dominat pathogenic mechanism in thyroid cancer is the activation of the MAPK and PI3K/Akt pathways caused by BRAFV600E mutation, RAS mutation or RET mutation." (PMID 35198054, 2022). "In patients with previously treated RET fusion‐positive thyroid cancer, the percentages who had a response were 89% for pralsetinib and 79% for selpercatinib, respectively." (PMID 36254250, 2022). "In the phase II, 122 MTC patients and 20 RET fusion positive thyroid cancer patients were included in the safety analysis." (PMID 35422765, 2022). "Molecular analyses in early childhood thyroid cancer cases revealed an extremely high prevalence of genome rearrangements between the Rearranged During Transfection (RET) gene and the PTC3 gene (RET/PTC3 rearrangement) located on the same chromosome 10." (PMID 36551665, 2022). "Mutations that disrupt the disulfide network in the extracellular domain (ECD) of RET drive multiple endocrine neoplasia type 2A (MEN2A), a hereditary syndrome associated with the development of thyroid cancers." (PMID 35985422, 2022). "Herein, RET fusions defined a unique subset of alterations across multiple tumor types (>15 including NSCLC and multiple subtypes of thyroid cancer) targeted by pralsetinib, validating RET as a tissue-agnostic target." (PMID 35962206, 2022). "Vandetanib, an established inhibitor of VEGFR, EGFR, and RET kinases, is approved for the treatment of certain thyroid cancers." (PMID 34551970, 2022). "Sixty-one MTC patients who experienced previous treatment with cabozantinib and/or vandetanib, 23 naïve MTC patients and 11 patients with RET fusion positive thyroid cancer were included in the efficacy analysis." (PMID 35422765, 2022). "In CCDC6-RET–rearranged thyroid cancer cells, we found activation of ERK signaling after RET inhibition." (PMID 35510953, 2022). "We confirmed a rebound in pERK after RETi using a second RET fusion thyroid cancer cell line, CUTC48." (PMID 35510953, 2022). "Since its discovery and subsequent pathway characterization, RET alterations have been identified in numerous cancer types and are most prevalent in thyroid carcinomas and non-small cell lung cancer (NSCLC)." (PMID 35957881, 2022). "Expression of human CCDC6-RET in zebrafish was associated with robust thyroid proliferation, activation of ERK signaling, development of thyroid carcinoma within weeks, and adaptive resistance after exposure to a selective RET inhibitor." (PMID 35510953, 2022). "Brain metastases of thyroid carcinomas are rare, but they can be also effectively treated with RET inhibitors." (PMID 36358717, 2022). "While aberrant RET activity is primarily associated with thyroid carcinomas and NSCLC, abnormal RET signaling is also found in other tumor types, albeit at lower frequencies." (PMID 35957881, 2022). "The RET-inhibitory activity of these drugs was discovered later, driving their development as anti-thyroid cancer agents." (PMID 33419162, 2021). "Our results showed that the RET protein expression level was higher in TT cells than other types of thyroid cancer cells." (PMID 34207842, 2021).
thyroid cancer (continued). "Analysis of lung and thyroid cancer tissues showed a positive rate by RET fusion partners such as KIF5B and CCDC6, and their sensitivities were 100%." (PMID 34497761, 2021). "Several RET inhibitors have been approved for thyroid cancer therapy by the Food and Drug Administration (FDA)." (PMID 33419162, 2021). "Recently, selpercatinib (Retevmo) has been approved by the FDA to treat MTC as well as non-small cell lung cancer and advanced RET fusion-positive thyroid cancer." (PMID 34209165, 2021). "Based on the MTS data, the IC50 of datelliptium in the Nthy-ori-3-1 cell line was estimated to be 10 μg/mL, four-fold higher than that for TT cells, suggesting that this compound is selectively toxic against mutant RET-driven thyroid cancer." (PMID 34209165, 2021). "MAPK and PI3K/AKT pathways are dependent on activity of mutually exclusive RAS, BRAF and RET/PTC point mutations (BRAF/RAS/PIK3CA) and rearrangements (RET/PTC and TRK) which drive thyroid cancer oncogenesis." (PMID 34062862, 2021). "Based on these observations, RET has emerged as an attractive target for thyroid cancer treatments, and thus, RET inhibitors have been actively investigated." (PMID 33419162, 2021). "In thyroid cancer, mutations in activated BRAF, RAS, and RET-PTC fusion genes can cause the stimulation of the MAPK signaling pathway." (PMID 34689819, 2021). "Here, we performed an analysis on the role of FRMD5 in thyroid cancer, as we found significant discrepancies in FRMD5 expression between BRAF- and RET-mutated PTCs, as well other types of TCs (TCGA and microarray data analysis of clinical specimens)." (PMID 34201607, 2021). "Since the discovery of the RET gene aberration, there have been studies on the development of RET kinase inhibitors for treating thyroid cancer." (PMID 33419162, 2021). "Vandetanib, cabozantinib, lenvatinib, and sorafenib are multikinase inhibitors with RET-inhibitory activity that have been repurposed for thyroid cancer treatments." (PMID 33419162, 2021). "RET fusions are reported to be the most common observed alteration in children thyroid carcinoma, and appeared to occur in approximately 25–30% of sporadic pediatric PTC; these results further increase to nearly 45% in patients exposed to radiation." (PMID 34069605, 2021). "Selpercatinib is indicated in RET fusion-positive advanced non-small lung cancer (NSCLC), RET-mutant MTC, and RET fusion-positive thyroid cancer." (PMID 33419162, 2021). "Recently, quinazoline compounds, specific inhibitors of the RET thyrosine kinase pathway showed mild to significant anticancer efficacy in some tumor cell lines, including thyroid cancer, suggesting a possible future therapeutic potential in MEN2." (PMID 32326947, 2020). "Within the genomics of tumors, implication of the rearrangement of the RET proto-oncogene in thyroid cancer and amplification of MYC in cutaneous angiosarcoma after irradiation of the chest wall for breast cancer are known." (PMID 33019945, 2020). "This and the promising results from the ongoing phase I/II study of this agent highlight the importance of establishing diagnostic procedures to facilitate the routine clinical detection of somatic RET alterations in patients with thyroid cancer." (PMID 32292131, 2020). "RET fusions have been reported more commonly (and the BRAFV600E mutation more rarely) in pediatric than in adult thyroid cancer patients." (PMID 32326537, 2020). "Multi-targeted TKIs including cabozantinib and vandetanib have been clinically used in RET-driven lung and thyroid cancers, but their insufficient inhibition of RET and off-target toxicities limited broader application." (PMID 33109256, 2020). "PTC contributes to almost 80% of thyroid cancers and RET fusions are the most commonly detected gene fusions in PTCs15." (PMID 32345963, 2020).
thyroid cancer (continued). "Prior to this, two multi-kinase inhibitors that targeted RET had been approved for use in thyroid cancer, cabozantinib and vandetanib." (PMID 33479617, 2020). "The RET/PTC1 rearrangement was a common oncogenic alteration to be observed in childhood thyroid cancer cases after the Chernobyl nuclear power plant accident, which resulted in radiation exposures." (PMID 32751138, 2020). "Based on previous reports, there are currently several biomarkers that have clinical implications for thyroid cancer including RET/PTC, RAS, BRAF, PAX8-PPARγ, MicroRNAs (miR-221, 222, and 181b), and activation of telomerase reverse transcriptase (TERT)." (PMID 33247684, 2020). "In the treatment of RET-altered thyroid cancers, the ORRs were 73% and 69%, respectively, in treatment-naïve and previously treated RET-mutant MTCs patients, and 79% in previously treated thyroid cancers patients with RET fusion." (PMID 33109256, 2020). "In the present study, the majority of samples (86.7%) are diploid for the RET gene suggesting substantial genomic stability of this thyroid cancer histotype." (PMID 33383911, 2020). "About 25% of Thyroid Carcinomas of Medullary type occur in carriers of hereditary alterations in the RET gene." (PMID 33167350, 2020). "Subsequently, Moretti and coworkers proved that RET/PTC3 induces IDO1 expression through full activation of STAT1-IRF1 pathway, demonstrating a direct link between this immunosuppressive enzyme and the oncogenic activation of RET in thyroid carcinoma." (PMID 33986723, 2020). "The discovery of oncogenes that drive thyroid cancer (such as RET, RAS, and BRAF), and are aligned in the MAPK/ERK pathway has led to a new perspective of thyroid oncogenesis." (PMID 31482959, 2019). "This overlap of eight genes included two genes prioritized using our pipeline (RET and TG), that are of particular interest in thyroid cancer." (PMID 31614935, 2019). "RET: The Rearranged during Transfection (RET) proto-oncogene is frequently altered in thyroid cancer." (PMID 31540307, 2019). "The RET/PTC1 (CCDC6-RET) is the most common rearrangement, accounting for 60% of thyroid cancer with RET rearrangements, followed by RET/PTC3 (NCOA4-RET, 30%), and RET/PTC2 (PRKAR1A-RET, 5%)." (PMID 31835496, 2019). "Currently, multi-kinase inhibitors with activity against RET are FDA approved for thyroid cancers, and clinical trials are investigating their use in targeting RET fusions in lung and other solid cancers." (PMID 30446652, 2018). "Point mutations of BRAF and RAS genes as well as RET/PTC and PAX8/PPARγ chromosomal rearrangements were found in thyroid cancer 146, 152-154." (PMID 30595827, 2018). "Mutations within ECD of other RTKs have also been reported, including RET in thyroid cancer and KIT in gastrointestinal stromal tumor (GIST)." (PMID 29455648, 2018). "Incorporating these findings, recent American and European guidelines support the use of mutation testing of genes associated with thyroid cancer (BRAF, RAS, RET/PTC, PAX8/PPARG) in order to improve surgical decision making." (PMID 30249281, 2018). "In cell assays ponatinib has antiproliferative effects on human TT, MZ-CRC-1 and TPC-1 thyroid carcinoma cells that bear endogenous RET alleles and on NIH3T3 fibroblasts transfected with RET mutants." (PMID 30423915, 2018). "This polypharmacology approach has previously been demonstrated to be effective in RET-driven thyroid cancer, using drosophila as a model to identify kinases that are contributing to tumor growth and survival." (PMID 29262541, 2017). "The aberrant activation of MAPK pathway in thyroid cancer is driven by some genetic alterations, including BRAF, RAS, RET-PTC, and ALK mutations." (PMID 28709407, 2017). "Translocation were reported in two samples, one was in ALK in a lung cancer sample and the other in RET in a thyroid cancer case." (PMID 28371134, 2017).
thyroid cancer (continued). "We also detected a variant on RET, a gene connected to MEN2A syndrome that confers an extremely high penetrant risk of thyroid cancer." (PMID 28569218, 2017). "Focusing on the affected genes that were observed only in a single cancer type revealed that the RET gene was affected by high methylation in thyroid cancer (shown in cornflower blue)." (PMID 28178311, 2017). "This is consistent with previous findings in a RET-driven drosophila thyroid cancer model where inhibition of key nodes: RET, RAF, Src, and S6K, was required to inhibit thyroid tumor progression." (PMID 29262541, 2017). "Remarkably, a similar situation was observed for the RET gene in the thyroid cancer dataset; the expression of the RET oncogene was upregulated, whereas 5 tumor samples exhibited decreased copy numbers of RET." (PMID 28178311, 2017). "Common genetic alterations found in thyroid cancer include point mutation of the BRAF and RAS genes (seen up to 45% of patients) as well as RET/PTC and PAX8/PPARγ chromosomal rearrangements." (PMID 28117293, 2017). "In this study, ganetespib inhibited RAS/RAF/ERK and PI3K/AKT/mTOR signaling in four histologic types of thyroid cancer cell lines and decreased RET level in a MTC cell line." (PMID 28476040, 2017). "The multi-targeted kinase inhibitor ponatinib showed promising preclinical activity in thyroid carcinoma cells and in a RET-driven medullary thyroid carcinoma mouse model." (PMID 29262623, 2017). "Its selective abrogation has been indeed actively pursued and several types of molecular weapons have been developed to affect RET expression or activity for therapeutic purposes in thyroid cancer." (PMID 27351133, 2016). "Thyroid cancers harbor characteristic genetic alterations, including point mutations for proto-oncogenes (BRAF, NRAS, HRAS, KRAS) and chromosomal rearrangements (RET/PTC1, RET/PTC3, PAX8/PPARG), which vary with histologic subtype." (PMID 27871285, 2016). "It is regarded as the major oncogene involved in thyroid cancer, since RET rearrangements are detected in radiation-induced papillary thyroid carcinoma and gain-of-function mutations do segregate in inherited and sporadic medullary thyroid carcinoma." (PMID 27034161, 2016). "Through RET/PTC pathway in thyroid cancer cells, XB130 diminution results in spontaneous apoptosis and enhancement of cell death with stimulant." (PMID 27509056, 2016). "In contrast to thyroid cancer, in which RET rearrangement is one of the most common molecular alterations and can be found in up to 80% of tumors, RET rearrangements are present only in 1–2% of patients with NSCLC." (PMID 26187152, 2015). "Multiple receptor tyrosine kinases are overexpressed in thyroid cancer, including RET, rapidly accelerated fibrosarcoma (RAF) kinases, VEGF, mesenchymal epithelial transition factor, and epidermal growth factor." (PMID 26064704, 2015). "Deregulation of RET and hyperactivity of the RET kinase is intimately connected to several types of human cancers, most notably thyroid cancers, making it an attractive therapeutic target for small-molecule kinase inhibitors." (PMID 25944708, 2015). "Vandetanib and lenvatinib, which are FDA-approved RET kinase inhibitors with clinical efficacy against RET fusion-positive thyroid cancer, followed the same pattern and specifically inhibited only Lc2/ad cells viability." (PMID 26078337, 2015). "They blunted proliferation of RET/C634R and RET/M918T-transformed fibroblasts and of RET mutant thyroid cancer cells." (PMID 26046350, 2015). "In accordance with the pivotal role of RET in regulating the growth of thyroid cancer cells in tumor development, there are clinically available drugs for MTC therapy such as cabozantinib and vandetanib that inhibit the tyrosine kinase activity of RET." (PMID 26307103, 2015). "LAD1 has been identified as an overexpressed gene in BRAFmut thyroid carcinomas compared to those with a RET/PTC rearrangement." (PMID 25922907, 2015).